XACT (X active specific transcript)
Gene: Long non-coding RNA gene on chromosome X (113,616,300 to 114,059,289, reverse strand). Ensembl gene ENSG00000241743.
Gene Ontology:
Molecular function: pre-mRNA 5'-splice site binding
Biological process: mRNA 5'-splice site recognition; RNA processing
Cellular component: nucleolus; U1 snRNP